CYSLTR1 (cysteinyl leukotriene receptor 1)
Diseases named in the same sentence as CYSLTR1 in open-access papers (continued):
Sharing a sentence is not in itself a finding about the gene and the disease.
colon cancer (22 papers, 2008 to 2024). "In an AOM/DSS-induced colitis-associated colon cancer model, we found that female mice with global Cysltr1 gene disruption had less severe disease activity compared with wild-type mice." (PMID 28410235, 2017). "In a spontaneous model of colon cancer, CysLT1R disruption was associated with a reduced tumor burden in double-mutant female mice (ApcMin/+/Cysltr1−/−) compared to ApcMin/+ littermates." (PMID 28410235, 2017). "CYSLTR1 is upregulated in colon cancer patients and associated with poor prognosis." (PMID 32324757, 2020). "A previous study indicated that MMP9 activity and expression were reduced by a CYSLTR1 antagonist (montelukast), and that M2 macrophages enriched in leukotriene D4 promoted the migration and invasion of colon cancer cells by inducing MMP9 expression." (PMID 33323552, 2020). "LTD4 and PGE2 are known to mediate their responses on colon cancer cells through activation of their receptors, CysLTR1 and EP1-4." (PMID 27388564, 2016). "In a recent study on colon cancer cells, CYSLTR1 signaling induced β-catenin translocation and the activation of β-catenin target genes, resulting in increased proliferation and migration of colon cancer cells." (PMID 27475906, 2016). "Furthermore, CYSLTR1 expression was correlated with enhanced levels of anti-apoptotic proteins in colon cancer and CYSLTR1 transfection resulted in prolonged survival of Caco-2 cancer cells in vitro." (PMID 27475906, 2016). "Montelukast, an antagonist against CYSLTR1, inhibited cell proliferation of HCT-116 cells (a human colon cancer cell line) in a dose-dependent manner." (PMID 34299067, 2021). "Next, we used both the colitis-associated colon cancer (CAC) mouse model and spontaneous CC mouse model (ApcMin/+) with either the functional presence or functional absence of Cysltr1 (n = five mice per genotype)." (PMID 38549115, 2024). "Activation of CysLTR1 by LTD4 induces phosphorylation of the MAPK cascade in mesangial cells, airway smooth muscle cells, and human mast cells, and it has been found to affect cancer growth through a similar pathway in pancreatic and colon cancer." (PMID 39064957, 2024). "There was a significant decrease in the negative M values for the two CpG probes for CYSLTR1 in colon tumors (cg00813999 and cd26848126) and rectal tumors (cg16886259 and cg16299590) compared with matched normal samples." (PMID 36834820, 2023).
allergic rhinitis (14 papers, 2014 to 2025). Inflammation of the nasal mucous membranes caused by an IgE-mediated response to external allergens. "CYSLTR1 immunomodulation in allergic rhinitis was determined to involve a concurrent increase in the level of active, phosphorylated ERK1/2." (PMID 33614606, 2020). "Elucidation of the involvement of cysLTs in the immunopathogenesis of allergic rhinitis and some subtypes of bronchial asthma led to the development of cysLTR1 antagonists, which are used primarily in the therapy and prophylaxis of these conditions." (PMID 24971371, 2014). "Recognition of the cysLT/cysLTR1 axis in the immunopathogenesis of bronchial asthma, as well as allergic rhinitis, provided the impetus for development of selective antagonists of cysLTR1." (PMID 24971371, 2014). "Furthermore, the cysteinyl leukotriene/cysteinyl leukotriene receptor 1 (cysLT/cysLTR1) axis is widely known in the immunopathogenesis of bronchial asthma as well as allergic rhinitis." (PMID 36012941, 2022). "There was also research reporting that polymorphism of rs321029 on CYSLTR1 gene was not related to the susceptibility and severity of allergic rhinitis in children, but it is closely related with the efficacy of montelukast on allergic rhinitis." (PMID 36911417, 2023).
colorectal cancer (10 papers, 2013 to 2024). A primary or metastatic malignant neoplasm that affects the colon or rectum. "Cysteinyl leukotriene receptor 1 (CysLT1R) has been shown to be up-regulated in the adenocarcinomas of colorectal cancer patients, which is associated with a poor prognosis." (PMID 28410235, 2017). "Our study is the first to show that the methylation and gene expression profiles for CYSLTR1/CYSLTR2 receptors together to investigate their role in colorectal cancer progression and metastasis using three independent in silico datasets and one clinical cohort." (PMID 36834820, 2023).
breast carcinoma (9 papers, 2016 to 2024). "Increased expression of CYSLTR1 has been reported in colorectal, gastric and breast cancers, and its high expression is associated with decreased survival in these cancer patients." (PMID 34299067, 2021). "High expression of CysLTR1 has been reported in pancreatic, colorectal, gastric, and breast cancers, with some studies linking high expression levels to reduced survival of patients with cancer." (PMID 39064957, 2024).
allergic disease (7 papers, 2011 to 2023). An immune response that occurs following re-exposure to an innocuous antigen, and that requires the presence of existing antibodies against that antigen. "The HWE equilibrium law was followed by the frequency distributions of the following polymorphisms in allergy patients: CYSLTR1 rs320995, GSDMB rs7216389, GPIIIa rs5918, GP1BA rs6065, PEAR1 rs12041331, PAI-1 rs1799762, and TNF-α rs1800629 (p > .05)." (PMID 36911417, 2023). "Pranlukast is a cysteinyl leukotriene receptor-1 antagonist that reduces bronchospasm caused by an allergic reaction, usually with asthmatic individuals." (PMID 22432004, 2012).
prostate carcinoma (7 papers, 2013 to 2023). A carcinoma that arises from epithelial cells of the prostate gland. "Leukotriene D4 (LTD4) stimulates the proliferation of endothelial cells through cysteinyl leukotriene receptor 1 (CysLT1R), which was shown expressed highly in many cancers (e.g., prostate cancer, brain cancer, neuroblastomas, and CRC)." (PMID 26967051, 2016).
COVID-19 (6 papers, 2021 to 2025). A disease caused by infection with severe acute respiratory syndrome coronavirus 2. "This study identified CCR5, CYSLTR1, and KLRG1 as efficient diagnostic biomarkers for severe COVID-19 using machine learning and revealed immune regulatory features across COVID-19 progression and recovery." (PMID 40444276, 2025). "Given the abnormal expression of CYSLTR1 and its potential involvement in COVID-19-related inflammation, leukotriene receptor antagonists hold promise as adjunctive therapies for severe COVID-19 patients." (PMID 40444276, 2025). "In summary, CCR5, CYSLTR1, and KLRG1 not only demonstrate significant diagnostic value for identifying severe COVID-19 patients but also play critical roles in modulating immune cell activation, differentiation, and function." (PMID 40444276, 2025). "Expression analysis revealed significant differential expression of CCR5, CYSLTR1, and KLRG1 between COVID-19 ICU and non-ICU groups." (PMID 40444276, 2025).
uveal melanoma (5 papers, 2020 to 2023). A melanoma derived from melanocytes of the uveal tract. "A study assessing data of 80 primary uveal melanoma samples in The Cancer Genome Atlas (TCGA) showed that higher expression of CYSLTR1 and CYSLTR2 genes were significantly associated with poorer disease-free survival and overall survival." (PMID 35008546, 2021).
atopic dermatitis (4 papers, 2017 to 2025). "Montelukast, a CYSLTR1 antagonist, effectively treats inflammatory disorders, such as rheumatoid arthritis, multiple sclerosis, and atopic dermatitis." (PMID 38617532, 2024).
atopic asthma (3 papers, 2016 to 2019). An asthma that is characterized by symptoms that are triggered by an allergic reaction caused by inhaled allergens such as dust mite allergen, pet dander, pollen and mold. "In addition, the CYSLTR1 gene, located at Xq13-21.1, has been associated with atopic asthma." (PMID 27990118, 2016). "The CYSLTR1 gene, located at Xq13-21.1, has been examined in atopic asthma." (PMID 27990118, 2016). "The presence of SNPs in both the CYSLTR1 and CYSLTR2 genes may increase the risk for atopic asthma." (PMID 27990118, 2016). "For example, while variability in the genes encoding drug targets such as the cysteinyl leukotriene 1 (CYSLTR1) and 2 (CYSLTR2) receptor genes may both contribute to risk for atopic asthma in some populations, only the cysteinyl leukotriene 1 (CYSLTR1) receptor is targeted by LTMs." (PMID 27990118, 2016). "Early studies of the effect of amino acid substitutions in the CYSLTR1 and CYSLTR2 receptor genes in atopic asthma were based on a personalized medicine hypothesis." (PMID 27990118, 2016).
Cerebral ischemia (3 papers, 2017 to 2024). Restriction of arterial blood supply to the brain associated with insufficient oxygenation to support the metabolic requirements of the tissue. "Indeed, CysLTR-1 was involved in glial scar formation during the chronic phase after focal cerebral ischemia, and CysLTR-1 antagonist, but not CysLTR-2, was able to reduce the astrocyte response in the subacute phase after brain ischemia." (PMID 28607533, 2017).
chronic asthma (3 papers, 2018 to 2022). An asthma that is characterized by the development of persistent airway inflammation and recurrent attacks of breathlessness and wheezing, which vary in severity and frequency. "Intriguingly, it has been demonstrated that management of chronic asthma by long-term use of CysLTR1 antagonists, like the U.S. Food and Drug Administration (FDA)-approved zafirlukast, significantly decreases the risk of several cancer types." (PMID 35408930, 2022). "Zafirlukast is currently used as a CysLTR1 antagonist in the treatment of chronic asthma and affects leukotriene-mediated eicosanoid inflammatory signaling." (PMID 35408930, 2022). "Recent studies also suggests the importance of CD49d+/cysteinyl leukotriene receptor 1 (CysLTR1) + polymorphonuclear neutrophils for FcεRI expression on mouse lung DCs and subsequent chronic asthma development." (PMID 30513770, 2018).
Cognitive impairment (3 papers, 2021 to 2025). Abnormal cognition is characterized by deficits in thinking, reasoning, or remembering. "Indeed, the CysLTR1 antagonist pranlukast is shown to mitigate the neuronal dysfunction and cognitive impairment associated with Aβ." (PMID 40507859, 2025). "Antagonising CysLTR1 in turn mitigated the resultant cognitive deficit." (PMID 40507859, 2025).
injury (3 papers, 2018 to 2022). Damage inflicted on the body as the direct or indirect result of an external force, with or without disruption of structural continuity. "In our study, we also found that Cysltr1 expression was higher in model of APAP-overdose-induced liver injury than the saline group." (PMID 31620001, 2019). "The expression of Cysltr1 was significantly induced in the hepatic ischemia–reperfusion injury and aluminum-overload-induced liver injury." (PMID 31620001, 2019). "Upregulation of cysteinyl leukotriene receptor 1 expression in the NPC niche is also induced by traumatic brain injury as wells as cerebroventricular microinjection of the immunogenic zymosan A BioParticles." (PMID 29760681, 2018).
ischemia (3 papers, 2017 to 2024). A hypoperfusion of the BLOOD through an organ or tissue caused by a PATHOLOGIC CONSTRICTION or obstruction of its BLOOD VESSELS, or an absence of BLOOD CIRCULATION. "Inhibition of CysLTR1 or CysLTR2 protects against LPS or ischemia-induced microglial inflammation and brain injury." (PMID 37361996, 2023). "In vitro, CysLTR-1 mediates astrocyte proliferation after mild ischemia, whereas CysLTR-2 mediates astrocyte death after more severe ischemia." (PMID 28607533, 2017). "Neuroprotection is provided by the CysLTR1 antagonist Montelukast and the CysLTR2 antagonist HAMI3379, as they inhibit ischemia-induced microglial activation and pro-inflammatory cytokine release." (PMID 37361996, 2023).
adenoma (2 papers, 2017 to 2023). A neoplasm arising from the epithelium. "The Cysltr1−/− colonic polyps exhibited low-grade dysplasia, while wild-type polyps had an adenoma-like phenotype." (PMID 28410235, 2017). "CYSLTR1 and CYSLTR2 expression were significantly higher and lower in the primary tumor samples than in the adenoma and normal samples, but it was higher and lower in the metastatic specimens than in the primary tumor samples, respectively." (PMID 36834820, 2023). "Interestingly, the negative M-value for the CpG probe for CYSLTR1 genes was significantly lower for primary tumors than for adenoma and matched normal tissues." (PMID 36834820, 2023).
airway hyperresponsiveness (2 papers, 2016 to 2023). "Accordingly, 1 μM WRW4 abolished the beneficial effects of RvD2 on TNF-α-induced activation of the 5-LOX/CysLTR1 pathway as well as TNF-α-induced airway hyperresponsiveness." (PMID 27935998, 2016). "The major findings of this study include (i) the resolving mode of action of RvD2 on complementary membrane and cellular inflammatory biomarkers such as CysLTR1, 5-LOX, p38-MAPK and AP-1; (ii) the broncho-modulatory role of RvD2 on LTD4- and TNF-α-induced airway hyperresponsiveness." (PMID 27935998, 2016).
autoimmune disease (2 papers, 2017 to 2024). A disorder resulting from loss of function or tissue destruction of an organ or multiple organs, arising from humoral or cellular immune responses of the individual to their own tissue constituents. "These mechanistic insights strengthen the proposition that CYSLTR1 holds substantial promise as a therapeutic target, not only for psoriasis but also for autoimmune diseases underpinned by the dysregulation of Th17 cells." (PMID 38617532, 2024).
esophageal squamous cell carcinoma (2 papers, 2016 to 2020). Esophageal squamous cell carcinoma (ESCC) is a type of esophageal carcinoma (EC) that can affect any part of the esophagus, but is usually located in the upper or middle third. "Expression of LTB4R, LTB4R2, CYSLTR1 and CYSLTR2 was analyzed by immunohistochemistry (IHC) and quantitative reverse transcription-polymerase chain reaction (qRT-PCR) in biopsy samples of 19 patients with esophageal squamous cell cancer and 9 sex- and age-matched patients with functional dyspepsia." (PMID 27475906, 2016). "We aimed to investigate the expression of LTB4R, LTB4R2, CYSLTR1 and CYSLTR2 in esophageal squamous cell carcinoma and adjacent non-transformed squamous epithelium of the esophagus, as well as in control biopsy samples from esophageal squamous epithelium of patients with functional dyspepsia." (PMID 27475906, 2016).
Hepatic fibrosis (2 papers, 2024). The presence of excessive fibrous connective tissue in the liver. "Hepatic granulomatous inflammation, hepatic fibrosis and IL-4 production in the liver was significantly reduced in mice lacking cysLTR1 during chronic schistosomiasis, while reduced liver pathology was observed during acute schistosomiasis." (PMID 38840916, 2024).
multiple sclerosis (2 papers, 2024). A progressive autoimmune disorder affecting the central nervous system resulting in demyelination. "CYSLTR1 antagonists have previously been found to be protective in rodent models of brain trauma, stroke, multiple sclerosis, Parkinson’s disease and AD." (PMID 38550989, 2024).
myocardial infarction (2 papers, 2022 to 2024). Gross necrosis of the myocardium, as a result of interruption of the blood supply to the area, as in coronary thrombosis. "This study aims to investigate the effects of montelukast, a CysLTR-1 antagonist, in a mouse model of myocardial infarction (MI)." (PMID 38337010, 2024).
pancreatic cancer (2 papers, 2021). "We found that LTD4 treatment of pancreatic cancer cell lines with high expression of CYSLTR1 led to cellular proliferation with ERK1/2 phosphorylation." (PMID 34299067, 2021). "Conversely, leukotriene D4 (LTD4), an agonist of CYSLTR1, increased cellular proliferation of pancreatic cancer cells with an accumulation of phospho-ERK1/2." (PMID 34299067, 2021).
pancreatic ductal adenocarcinoma (2 papers, 2021). An infiltrating adenocarcinoma that arises from the epithelial cells of the pancreas. "In our cohort, pancreatic ductal adenocarcinoma patients with high CYSLTR1 expression showed a significantly unfavorable clinical outcome compared with those with low expression." (PMID 34299067, 2021).
schistosomiasis (2 papers, 2024). An infectious disease caused by parasitic trematodes of the genus Schistosoma that colonize human blood vessels and release eggs that can cause granulomatous reactions leading to acute (swimmer's itch or acute schistosomiasis syndrome) or chronic disease. "In conclusion, the present study demonstrated that cysLTR1 is a potential target for host-directed therapy to ameliorate fibrogranulomatous pathology in the liver during chronic and acute schistosomiasis in mice." (PMID 38840916, 2024). "The present study aimed to investigate the role of cysLTR1 during experimental acute and chronic schistosomiasis using cysLTR1-/- mice, as well as the use of cysLTR1 inhibitor (Montelukast) to assess immune responses during chronic Schistosoma mansoni infection." (PMID 38840916, 2024). "We show that the disruption of cysLTR1 is dispensable for host survival during schistosomiasis, suggesting an important role cysLTR1 may play during early immunity against schistosomiasis." (PMID 38840916, 2024).
Stroke (2 papers, 2017 to 2024). Sudden impairment of blood flow to a part of the brain due to occlusion or rupture of an artery to the brain. "Taken together, these data add new evidences for the neuroprotective effects of CysLTR-1 antagonists and highlight the need for further studies that will define the possibility to use CysLTR-1 antagonists for treatment of stroke patients." (PMID 28607533, 2017).
acute liver failure (1 paper, 2019). Rapid deterioration of liver function causing encephalopathy and coagulopathy. "Pharmacological inhibition of Cysltr1 by montelukast ameliorated APAP-induced acute liver failure." (PMID 31620001, 2019).
Anxiety (1 paper, 2021). Intense feelings of nervousness, tension, or panic often arise in response to interpersonal stresses. "Gabrr1 and Cysltr1 has few previous studies related to anxiety and depression." (PMID 34276303, 2021).
Erythema (1 paper, 2024). Redness of the skin, caused by hyperemia of the capillaries in the lower layers of the skin. "Notably, CYSLTR1 KO mice exhibited reduced PASI scores and delayed disease progression, as evidenced by improvements in skin erythema, scale, and thickness compared to WT mice." (PMID 38617532, 2024).
Hyperglycemia (1 paper, 2024). An increased concentration of glucose in the blood. "Endothelial activation induced by hyperglycemia and inflammation increased CysLTR1 expression, triggering autophagy within two to six hours, IL-1β production, loss of junction integrity, decreased TER, and increased leukocyte migration within six to 24 hours." (PMID 39504050, 2024). "This study investigated the role of CysLTR1 antagonism by montelukast in mitigating the detrimental effects of hyperglycemia and proinflammatory signaling on retinal microvascular endothelial cells (HRECs)." (PMID 39504050, 2024). "Therefore this study aims to understand the CysLTR1 signaling in retinal endothelial cells using a well-established model of endothelial activation induced by hyperglycemia combined with proinflammatory signaling." (PMID 39504050, 2024). "To this end we examined whether CysLTR1 is necessary for montelukast in alleviating inflammation under the influence of hyperglycemia and TNF-α." (PMID 39504050, 2024). "Although our studies did not attempt to study how hyperglycemia and TNF-α aid CysLTR1-associated changes in HRECs, it may be speculated that hyperglycemia and TNF-α–mediated stress might elevate LTE4, as also observed in preclinical models and diabetic subjects." (PMID 39504050, 2024).
hypersensitive reactions (1 paper, 2020). "In contrast, the third most DM gene is the protein-coding cysteinyl leukotriene receptor 1 (CYSLTR1) gene, which is normally involved in allergic and hypersensitive reactions." (PMID 32038103, 2020).